CASP9 (caspase 9)
Diseases named in the same sentence as CASP9 in open-access papers (continued):
Sharing a sentence is not in itself a finding about the gene and the disease.
tumor (continued). "Increased expression levels of cleaved caspase-9, cleaved caspase-3 and phosphorylated JNK were observed in tumours derived from SW480-NRBP1 cells compared with tumours derived from SW480-GFP cells." (PMID 29567997, 2018). "In the chemosensitive group, survivin expression was decreased and CASP-9 expression was increased, which led to c-CASP-3 activation and increased tumor cell apoptosis." (PMID 29549251, 2018). "They reduced the cleavage of caspase-9 and growth suppression by ASC induction, indicating that gap junctions were possible mediators of ASC-dependent apoptosis in HT1080 tumor cells in high cell density conditions." (PMID 28056049, 2017). "This was accompanied by increased expression levels of cytochrome c, caspase-3, caspase-8, and caspase-9 in JHU-22miR124 cultured cells and tumor xenografts." (PMID 28212569, 2017). "Western blot analysis for caspase-3 and caspase-9 demonstrated that pro-caspase-3 and pro-caspase-9 were subjected to more proteolytic processing in the shRNA-XIAP-AS1 tumor tissues than in the control tumor tissues." (PMID 28792527, 2017). "Next, we measured the expression levels of cleaved caspase-3 and caspase-9 in the XIAP-AS1 knockdown and control tumor tissues." (PMID 28792527, 2017). "And western blot analysis illustrated that cleavage of Caspase-3, PARP, Caspase-8, and Caspase-9 were significantly induced by ACT, and LC3B-I/II and Beclin 1 were also potentiated due to ACT treatment in tumor samples." (PMID 29348843, 2017). "To further exploit the anti-tumor mechanism of APG and TRAIL, we detected the activation of caspase-8, caspase-9 and caspase-3." (PMID 27752089, 2016). "Since our results are in agreement with the induction of the intrinsic apoptotic pathway in tumor biopsies from mice injected subcutaneously with HCMV-infected HepG2 cells, we assessed cytochrome c-induced caspase-9 activation in our xenografted murine model." (PMID 27626063, 2016). "Consistent with this, we observed an increase in Caspase 9 expression in HHT-treated 786-O cells, as well as morphologic tumor necrosis." (PMID 26219258, 2015). "Functional studies showed that only IL-24wt significantly inhibited cell growth and colony formation, induced G2/M cell-cycle arrest, and activated caspase-9, PARP, and JNK, indicating that phosphorylation is required for IL-24 to exert anti-tumor effects." (PMID 26009991, 2015). "Apollon knockdown also enhanced cisplatin/docetaxel-induced activation of caspase-8 (extrinsic pathway) and caspase-9 (intrinsic pathway) in ESCC cells and xenograft tumor models." (PMID 25216531, 2014). "IHC also showed that caspase-1, caspase-3, caspase-6, caspase-9, and PARP proteins were mainly expressed in the cytoplasm of tumor tissue." (PMID 24204937, 2013). "All these data, combined to the specific targeting of caspase-9/PP2A interaction and the development of cell penetrating peptides as targeted therapies, support our innovative potential anti-tumour therapeutic approach." (PMID 23637769, 2013). "Using the cell-penetrating peptides blocking caspase-9/PP2A interactions, we have demonstrated that DPT-C9h had a strong therapeutic effect in vitro and in vivo in mouse models of tumour progression." (PMID 23637769, 2013). "Enhanced activity of caspase-9 and cytochrome c release was observed in LA-pre-treated RKO tumor cells that support the proposal that apoptosis in these cells are mediated by mitochondrial pathway." (PMID 20868498, 2010). "Here we showed that MnSOD siRNA increased caspase-9 activation and drug-induced apoptosis through an MEK1-ERK1/2-dependent mechanism, thereby enhancing the ability of chemotherapeutic agents to kill tumour cells." (PMID 18594523, 2008).
tumor (continued). "Therefore, the deficient activation of caspase-9 might contribute to the clinically known resistance of human RCC against IR and also argues against an effective combination therapy with TRAIL and IR in this tumour type." (PMID 12771998, 2003). "We would conclude by suggesting that caspase-9, and, in particular, DFF45 are good candidates for the supposed tumour suppressor on 1p36.2-3." (PMID 11870543, 2002). "In this study, the effect of genistein on the expression of miR-27a as a tumor suppressor, miR-151 as an oncogene, and genes involved in apoptosis and autophagy, including ATG12, Beclin1, Caspase 3, and Caspase 9, in EJ138 BC cells was investigated using real-time PCR." (PMID 40718456, 2025). "Consistent with our in vitro findings, Western blot analysis of tumor tissues revealed that CDN treatment downregulated p-JAK1/2 and p-STAT3 expression while upregulating the pro-apoptotic proteins Bax, cleaved caspase-3, and cleaved caspase-9." (PMID 41585878, 2025). "We assessed the expression of apoptosis-related proteins (caspase-3, caspase-8, and caspase-9) in tumours obtained from nude mice treated with or without ART using immunohistochemistry." (PMID 38773551, 2024). "Moreover, in the rNDV‐TRAIL group, the activation levels of Bax/Bcl‐2 ratio, Cytochrome C, and caspase 9 of the intrinsic signaling pathway were increased compared to the rNDV group in both HCT116 and HT‐29 tumor tissues." (PMID 37843231, 2023). "The phosphorylated AKT (p-AKT) can activate multiple downstream signaling molecules, inhibit tumor cell autophagy through mTOR, phosphorylate MADD, caspase-3, caspase-9, phosphorylate FOXO-1 to control the cell cycle, and promote tumor cell growth and/or metastasis." (PMID 37070074, 2023). "The as-synthesized Fe-CDs could selectively induce tumor cells apoptosis by BAX/Caspase 9/Caspase 3/PARP signal pathways and activate antitumoral macrophages by inhibiting the IL-10/Arg-1 axis, contributing to its significant tumor immunotherapy effect." (PMID 37978538, 2023). "Western blotting of tumor samples showed that the combination treatment with CQ increased heat treatment induced the accumulation of LC3-II and cleaved-caspase 9, and retarded heat treatment induced the up-regulation of TGF-β2, Smad2 phosphorylation and N-cadherin and down-regulation of E-cadherin." (PMID 36650834, 2023). "Selenium plays an important role in increasing the expression levels of Caspase-1, Caspase-3, Caspase-8, and Caspase-9 and decreasing the expression levels of Bcl-2 and LC3, which promote the development of cellular pyroptosis and apoptosis and increase the rate of tumor cell death." (PMID 37994159, 2023). "CASP9 expression levels were not significantly different between normal, tumor, and metastatic breast cancer tissues." (PMID 35845599, 2022). "In unmatched analyses of n = 43 primary and 11 nodal metastases, our data indicated that tumor cells in nodal metastases had higher levels of Ki-67, PARP, BAD, and cleaved caspase 9, suggesting a role for increased proliferation, DNA repair, and apoptosis within these metastatic cells." (PMID 35651606, 2022). "Additionally, the levels of cleaved caspase-9, -3, and -7 and PARP in tumor tissues were analyzed using Western blotting or immunohistochemistry staining." (PMID 35336106, 2022). "Compared to over-expression of FLIP-s or BCL-XL, expression of dominant negative caspase 9 was less effective at preventing tumor cell killing." (PMID 35136485, 2022). "In this study, it was observed that IL-10 blockade could increase the capacity of our adjuvant E7&IL-24 vaccine in eradicating tumor cells, which was further proved by an increase in the level of IFN-γ and caspase-9." (PMID 35752792, 2022).
tumor (continued). "For example, inhibiting the CASP9 signaling pathway can help tumor cells recognize their own mtDNA, efficiently secrete IFN-I after radiotherapy, promote the cross-presentation of DCs, and enhance the anti-tumor immunity mediated by CD8+ T cells." (PMID 35326602, 2022). "The expression of cleaved caspase-9 and cleaved caspase-3 proteins increased by 165% and 161%, respectively (p < 0.05), in the CDDP treatment group compared to the tumor group, but these increases were significantly (p < 0.05) lower than those observed in the RTP-H treatment group." (PMID 35269987, 2022). "We found that the significant delay in tumor growth in xenograft mice treated with heat-killed B. bifidum MG731, L. casei MG4584, and L. reuteri MG5346 was mediated by the increased levels of caspase-9, -3, and -7 and PARP in tumor tissues derived from xenograft." (PMID 35336106, 2022). "Crucially, we observed the upregulation of the cleaved caspase 9 fragment at 35 kDa as well as the cleaved caspase 6 fragment at 15 kDa, but not of the full-length proteins in the hot tumor subgroup." (PMID 36139700, 2022). "TAX promoted the expression of the pro-apoptotic molecules such as Bax, Caspase-3, Caspase-9, Cyt-C and inhibited the expression of the anti-apoptosis molecules such as Bcl-2 and PARP1, indicating that TAX efficiently induced apoptosis in tumor cells in mRNA or protein levels." (PMID 36230568, 2022). "In addition, knockdown of NIK dramatically promoted IR‐induced cleavage of caspase 9, caspase 7, caspase 3, and PARP in PELI1‐knockdown tumor cells, which was consistent with the apoptosis flow cytometry assay results." (PMID 34738714, 2022). "In the tumor tissues of SMMC-7721-xenotransplanted BALB/c nude mice, Tf-LP-ERN strongly enhanced the expression levels of Bax, Bad, PUMA, cleaved RARP-1, cleaved caspase-3 and caspase-9, and decreased the expression level of Bcl-2." (PMID 34513705, 2021). "A total of 24 pyroptosis-related genes shown significantly different expression between normal and tumor tissues in COAD and seven genes (CASP4, CASP5, CASP9, IL6, NOD1, PJVK, and PRKACA) screened by univariate and LASSO cox regression analysis were used to construct the risk model." (PMID 34938319, 2021). "Furthermore, PBMF treatment notably upregulated the mRNA expression levels of GSK-3β, E-cadherin, Bax, Caspase-3, and Caspase-9 but substantially downregulated those of β-catenin, N-cadherin, MMP-2, MMP-9, Snail, and Cyclin D1 in tumor tissues." (PMID 33964908, 2021). "In addition, the levels of cleaved casp-3 and cleaved casp-9 were elevated and the levels of MRP1 and MDR1 were decreased in mice tumor tissues of the sh-SNHG6 group with PTX treatment in comparison to the control groups." (PMID 32782439, 2020). "In tumor cells, AKT can be transformed into pAKT through phosphatidylinositol 3-kinase phosphorylation, and pAKT can promote cell proliferation and inhibit cell apoptosis by activating caspase 9, Bad, FOXO, GSK-3β and IKK by phosphorylation." (PMID 33221748, 2020).
tumor (continued). "The inhibitory pathway of anthocyanin was explored by assessment of tumour cell mitochondrial membrane potential (MMP), the caspase-3 and caspase-9 activity, as well as the cell energy metabolism in terms of the glucose uptake, the NAD+/NADH ratio and the ATP level." (PMID 33059637, 2020). "Then, in the sensitive group, the expression level of survivin, an inhibitor of apoptosis, is decreased, while the expression level of CASP-9, an effector of apoptosis, is increased, subsequently triggering the caspase cascade and leading to c-CASP-3 activation and enhanced tumor cell apoptosis." (PMID 29549251, 2018). "Moreover, expression of the cleaved caspase-8, caspase-9 and PARP in tumor sections were also increased by AZOX in the xenograft mice model." (PMID 28567017, 2017). "Finally, CMLD-2 treatment resulted in greater mitochondrial perturbation, activation of caspase-9 and -3 and cleavage of PARP in tumor cells compared to normal cells." (PMID 28855578, 2017). "At 25 days after injection of HepG2 cells that were transfected with siRNA-TM4SF1, tumor expression of MMP-2, MMP-9, and VEGF were significantly lower, but tumor expression of caspase-3, caspase-9, and TIMP were higher, relative to injection with control cells (p < 0.01 for all comparisons)." (PMID 27153056, 2016). "Herein, overexpression of BM742401 resulted in the activation of Caspase 9 and Caspase 3, but not Caspase 8, showing that the tumor suppressive function of BM742401 in CLL was mediated by activation of intrinsic apoptosis pathway." (PMID 27689399, 2016). "Knock down of apoptosis-inducing factor (AIF) protected tumor cells from the drug combination, whereas blockade of caspase 9 signaling did not." (PMID 27379204, 2016). "Therefore, we employed Western blot to assess the expression levels of apoptotic proteins involved in the extrinsic (caspase-8) and the intrinsic (caspase-9 and PARP) pathways, in the tumor tissues at 24 h after cryoablation." (PMID 24818132, 2014). "Caspase-9 protein was detected in the cytoplasm and nucleus of ESFT, expression was low in 39/59 (66%) and high in 20/59 (34%) of tumours." (PMID 25157404, 2014). "In contrast to c-Jun, p73 and Casp-9, there was no significant aberration with N-ras expression irrespective of either tissue or tumor types." (PMID 22974165, 2012). "In contrast to other tumour types, activation of initiator caspase-9 was not detectable in our RCC model system after exposure to TRAIL and/or IR." (PMID 12771998, 2003). "Furthermore, L. plantarum-derived exopolysaccharides increase reactive oxygen species levels and upregulate the expression of the pro-apoptotic proteins such as Bax, caspase-3, caspase-8, and caspase-9, thus contributing to the apoptosis in HT-29 CRC tumor cells." (PMID 39653811, 2025). "Tumor growth inhibition mediated by HG was related to the induction of apoptosis through the mitochondrial pathway, as exemplified by disrupting MMP, inducing the generation of ROS, elevating the activation of caspase-9 and caspase-3, upregulating Bax, and downregulating Bcl-2, Bcl-xL, and Survivin." (PMID 38962311, 2024).
tumor (continued). "In a variety of tissue cells and tumor cells, the activation of GSK-3β may further activate apoptosis-related protein kinase family caspase 3 and caspase 9, induce decomposition of nucleoprotein and shear fracture of DNA strand, and ultimately mediate apoptosis." (PMID 30237226, 2019). "In addition to this, increased expression of both cleaved caspase-9 as well as cleaved caspase-3 was seen in the tissue sections of the ZnO-PBA, curcumin and ZnO-PBA-Curcumin administered animals compared to control tissue (untreated tumor-bearing animals)." (PMID 31032117, 2019). "Since some studies showed the anti-tumor effect of luteolin may be related to apoptosis, we employed FCM to determine the level of apoptosis and confirm the expression of proteins related to apoptosis, such as bcl-2, bax, caspase-9 and so forth." (PMID 28977853, 2017). "Functionally, stable overexpression of BM742401 resulted in inhibition of cellular proliferation and enhanced apoptosis through caspase-9-dependent intrinsic but not caspase-8-dependent extrinsic apoptosis pathway, suggesting a tumor suppressor role of BM742401 in CLL." (PMID 27689399, 2016). "Cleaved caspase 1 (p20) (P < 0.05), cleaved caspase 3 (p17, 19) (P < 0.01), cleaved caspase 8 (p18, 43) (P < 0.05), cleaved caspase 9 (p37, 39) (P < 0.05), and TNF-stimulated gene 6 protein (TSG6) (P < 0.05) could be significantly identified in Sal-YB1-treated tumor mass by Western blotting." (PMID 26286454, 2015). "First, PDT can activate caspase-8 and caspase-9, and then the active form of caspase-8 and caspase-9 initiates caspase-3 and caspase-6 activation to subsequently activate the remainder of the caspase cascade, which degrades PARP, and finally leads to apoptosis of tumor cells." (PMID 24204937, 2013). "In the caspase family, caspase-1, caspase-3, caspase-6, and caspase-9 are major cascade activation proteins, and PDT initiates the apoptosis cascade reaction primarily by activating caspase-dependent intrinsic and extrinsic pathways; this cleaves PARP, ultimately leading to apoptosis of tumor cells." (PMID 24204937, 2013). "We examined apoptosis-inductive signalling in tumour cell death, and neither activation of caspase-9 via the mitochondrial system nor activation of caspase-8 via the cytoplasmic system, known as representative apoptotic signalling systems, were confirmed (data not shown)." (PMID 18087283, 2008). "Activation of caspase-9 in response to treatment with cytotoxic drugs is inhibited in NSCLC cells, which may contribute to the clinical resistance to chemotherapy shown in this type of tumor." (PMID 16796750, 2006). "Finally, CASP9 was not differentially expressed between the normal tissue and the tumor tissue." (PMID 35845599, 2022). "Previous studies have shown that several biologically active substances could induce tumor cell apoptosis, inhibiting tumor progression by modulating pro-apoptotic proteins and apoptotic proteins (Bax, Bcl-xl) and increasing caspase expression and activation (CASP3, CASP8, CASP9)." (PMID 32381120, 2020).